CCDC152 (coiled-coil domain containing 152)
Synonyms: LOC100129792; CH5400; LIST
Tractability: PROTAC: ubiquitination databases record sites on it.
Gene: Protein-coding gene on chromosome 5 (42,756,799 to 42,802,439, forward strand). Ensembl gene ENSG00000198865.
Subcellular location (Human Protein Atlas): Nucleoplasm; Cytosol
Gene Ontology:
Molecular function: protein binding
Genetic constraint (gnomAD): Loss-of-function variants: 8 observed, 6.49 expected, observed/expected ratio (o/e) 1.23, 90% interval 0.71 to 1.87. That is too few expected variants to judge how well the gene tolerates losing a copy. Missense variants: 72 observed, 78.45 expected, observed/expected ratio (o/e) 0.92, 90% interval 0.76 to 1.12. Synonymous variants: 26 observed, 23.84 expected, observed/expected ratio (o/e) 1.09, 90% interval 0.8 to 1.51.
Homologues: Orthologues: chimpanzee CCDC152 (100% identical), macaque CCDC152 (97% identical), pig CCDC152 (87% identical), dog CCDC152 (85% identical), rabbit CCDC152 (83% identical), guinea pig CCDC152 (80% identical), rat Ccdc152 (77% identical), mouse Ccdc152 (77% identical), tropical clawed frog CCDC152 (48% identical).
Diseases named in the same sentence as CCDC152 in open-access papers:
CCDC152 is named in the same sentence as 13 diseases in open-access papers, as found by Europe PMC text mining. Sharing a sentence is not in itself a finding about the gene and the disease. The quoted sentences say what the papers report.
colorectal adenocarcinoma (1 paper, 2021). The most common type of colorectal carcinoma. "The PCR products of the CCDC152 gene were low but detected in other cell lines including rhabdomyosarcoma RD cells, HEK293 cells, and human colorectal adenocarcinoma HT-29 cells." (PMID 34142161, 2021).
glioma (1 paper, 2021). A benign or malignant brain and spinal cord tumor that arises from glial cells (astrocytes, oligodendrocytes, ependymal cells). "On the other hand, CCDC152 gene expression was mostly observed in human neuroblastoma SH-SY5Y cells, glioma U-87MG cells and Jurkat cells." (PMID 34142161, 2021).
hepatoma (1 paper, 2021). "In the case of human hepatoma Li-7 cells, the decrease in SELENOP protein levels in whole-cell lysates was also induced by CCDC152 transfection without the significant change of SELENOP mRNA levels." (PMID 34142161, 2021).
tumor (3 papers, 2020 to 2024). "Notably, five DEG expression levels were correlated with prognosis in these three tumor types, including AXL, CCDC152, EVI2B, GLIPR1, and SERPING1." (PMID 32903590, 2020).
CCDC152 also shares sentences with these, for which no sentence is quoted: cancer (2 papers); bladder carcinoma (1); bladder urothelial carcinoma (1); bovine tuberculosis (1); lung carcinoma (1); melanoma (1); neuroblastoma (1); prostate adenocarcinoma (1); rhabdomyosarcoma (1).